BMP4 (bone morphogenetic protein 4)
Diseases named in the same sentence as BMP4 in open-access papers (continued):
Sharing a sentence is not in itself a finding about the gene and the disease.
pulmonary fibrosis (9 papers, 2010 to 2025). Chronic progressive interstitial lung disorder characterized by the replacement of the lung tissue by connective tissue, leading to progressive dyspnea, respiratory failure, or right heart failure. "In the present study, pirfenidone also reduced the levels of the BMP4 antagonist Gremlin1, which was previously implicated in the development of lung fibrosis, when stimulated by TGF-β1 and rhCTHRC1." (PMID 31185973, 2019). "By stimulation of mouse PLFs with TGF-β1, we found that BMP4 mRNA and protein levels were significantly decreased as demonstrated by qRT-PCR and Western blot, indicating that BMP4 deficiency is positively associated with fibroblast activation and lung fibrosis." (PMID 35915750, 2022). "Recently, Peng’s group has discovered that inhalation of BMP4 into lungs can restore normal lung regeneration and improve lung function in a murine lung fibrosis model." (PMID 39142248, 2024). "BMP4 protects rat pulmonary arterial smooth muscle cells from apoptosis and prevents pulmonary fibrosis." (PMID 39739870, 2024). "BMP4 has been shown to have antifibrotic effects in various models of fibrosis, such as pulmonary fibrosis, liver fibrosis, and renal fibrosis." (PMID 38017561, 2023). "Hence, we aimed to assess the gene expression of BMP4 along with the genes involved in the WNT pathway in the context of bleomycin-induced pulmonary fibrosis and after treatment with the iPSCs." (PMID 38017561, 2023). "Among those genes, we found that CAV1 and PECAM1 were specifically expressed in lung tissues, BMP4 and VEGFA were related to angiogenesis, FYN and SPP1 were related to immunity or inflammation, and COL1A1 was closely associated with pulmonary fibrosis according to the GeneCards database." (PMID 37794454, 2023). "By searching the 18 candidate hub genes in GeneCards database, we found that CAV1 and PECAM1 were specifically expressed in lung tissues, BMP4 and VEGFA were related to angiogenesis, FYN and SPP1 were related to immunity or inflammation, and COL1A1 was closely associated with pulmonary fibrosis." (PMID 37794454, 2023). "Others have shown an up-regulation of Gremlin, an inhibitor of BMP-4 signaling pathways, in idiopathic pulmonary fibrosis and have suggested that this increased expression of Gremlin may be a key event in the persistence of myofibroblasts in the lung interstitium." (PMID 20573231, 2010). "Although BMP members have been revealed to play an anti-fibrotic function in several different organs, BMP4 and BMP7 are the most intensively studied in pulmonary fibrosis." (PMID 39142248, 2024). "The authors showed that overexpression of BMP4 with an AAV system reversed bleomyin-induced murine lung fibrosis and promoted lung fibrosis resolution." (PMID 39142248, 2024). "Our findings indicate that BMP4 exerts its anti-fibrotic effects by regulating fibroblast proliferation, apoptosis, activation and differentiation via the inhibition of the ERK/p38 MAPK signaling pathway, and thus has a potential for the treatment of pulmonary fibrosis." (PMID 35915750, 2022).
brain tumor (8 papers, 2009 to 2022). "Here, we review current research associated with BMP4 in brain tumors, with an emphasis on pediatric malignant gliomas." (PMID 32102285, 2020). "Also, several extrinsic signaling molecules have already been linked to the loss of expression of AC133 associated with differentiation, notably in brain tumor stem cells with BMP-4, retinoic acid or oxygen." (PMID 21966538, 2011). "TGF-β and TGF family gene BMP4 could attenuate brain tumor stem cell proliferation through the SMAD pathway." (PMID 35891479, 2022). "Strategies to induce cancer stem cell differentiation have been widely used across various malignancies, such as the delivery of bone morphogenetic protein 4 (BMP4) to brain tumor initiating cells for astrocytic induction, rendering cancer stem cells more susceptible to chemotherapy." (PMID 32849207, 2020).
colitis (8 papers, 2021 to 2026). Inflammation of the colon. "Recent research on DSS-induced colitis found that expression patterns were associated with disease progression; specifically, BMP4 and Smad4 expression in the crypt was upregulated during early-stage DSS-induced colitis and downregulated during the late stage." (PMID 37391444, 2023). "The perturbation of epithelial Bmpr1a has been shown to amplify BMP4 levels in the context of dextran sodium sulphate (DSS)-inuced colitis." (PMID 37628872, 2023). "BMP4 expression was similar in the early and late stages of colitis, whereas BMP2 expression was considerably higher in the acute stage." (PMID 36500396, 2022). "We further checked the colon epithelium proliferation and Lgr5+ ISC maintenance ability in DSS-induced colitis treated with BMP4 recombinant protein and antibody at 7 days." (PMID 34692671, 2021). "Immunofluorescence labeling for Lgr5 showed that the Lgr5+ cells were upregulated in the DSS-induced colitis group treated with BMP4." (PMID 34692671, 2021). "The effects of BMP4 on the symptoms of colitis and intestinal epithelium proliferation and ISC maintenance in DSS-induced colitis were also investigated." (PMID 34692671, 2021). "Our study demonstrated the function and mechanism of BMP4 in the pathology of the DSS-induced colitis mouse model and suggested the therapeutic potential of BMP4 for the treatment of ulcerative colitis and other mucosal diseases." (PMID 34692671, 2021). "We investigated the expression of ID3 in DSS-induced colitis mice using BMP4 recombinant protein and anti-BMP4 treatment." (PMID 34692671, 2021). "Immunofluorescence labeling for Ki67 showed that DSS-induced colitis treated with BMP4 has a significantly enhanced proliferating epithelium cell layer when compared with DSS-induced colitis that is treated with antibody." (PMID 34692671, 2021). "Recent investigations into DSS-induced colitis have unveiled dynamic expression patterns correlating with disease progression, notably observing an upregulation of BMP4 and Smad4 in the crypt during the early stages, followed by a downregulation in the later stages." (PMID 37628872, 2023). "The administration of exogenous BMP4 supplement could alleviate DSS-induced colitis by restoring epithelium cellular proliferation and ISC function, suggesting the possible therapeutic function of BMP4 for ulcerative colitis." (PMID 34692671, 2021). "BMP4 recombinant protein treatment could preserve Lgr5+ ISCs, colon epithelium turnover, and could even alleviate the symptoms of colitis in experimental mice by targeting ID3." (PMID 34692671, 2021). "Furthermore, Bmp4+ fibroblasts in the berberine group exhibited enhanced collagen-Sdc1/4 signaling, a pathway critical for modulating epithelial barrier integrity and promoting mucosal regeneration in experimental colitis 50,51." (PMID 41356191, 2026). "Leedham and collaborators analyzed the role of BMP signaling in intestinal regeneration and showed a reduction of epithelial BMP-4 production and an increase in stromal GREM-1 production during colitis." (PMID 40319019, 2025). "Deletion of epithelial Bmpr1a enhances BMP4 in dextran sodium sulphate (DSS)-induced colitis, whereas inflammatory cytokines TNF-α and IL-1β both inhibit BMP4." (PMID 37391444, 2023). "Our results showed that BMP4 and SMAD4 were downregulated at the late stage of DSS-induced colitis, which is consistent with other studies we examined." (PMID 34692671, 2021). "Thus, in order to confirm the function of BMP4 on intestinal epithelium, we dynamically detected the intestinal epithelium proliferation and Lgr5+ ISCs in mice with DSS-induced colitis." (PMID 34692671, 2021). "In the present study, our results showed that upregulated SMAD4 and BMP4 expression was related to a more rapid colon epithelium renewal and Lgr5+ ISC maintenance ability during the first 3 days of DSS induced experimental colitis in mice." (PMID 34692671, 2021).
colitis (continued). "It was found that the reduced expression of BMP4 and BMPR1A was co-related with colon injury and inflammation in DSS-induced colitis, and the colonic inflammation and damage could be enhanced through deletion of BMPR1A." (PMID 34692671, 2021). "In conclusion, the present study showed that BMP4 could maintain epithelium cellular proliferation and the ISCs function through ID3 in mice with DSS-induced colitis." (PMID 34692671, 2021). "In addition, BMP4 treatment can alleviate the symptoms of DSS-induced colitis, although the disease symptoms were not significantly changed with BMP4-neutralized antibody treatment." (PMID 34692671, 2021).
embryonal carcinoma (8 papers, 2010 to 2023). A non-seminomatous malignant germ cell tumor characterized by the presence of large germ cells with abundant cytoplasm resembling epithelial cells, geographic necrosis, high mitotic activity, and pseudoglandular and pseudopapillary structures formation. "For example, BMP2 and BMP4 have been shown to interact with RA signalling to induce apoptosis of P19 embryonic carcinoma cells." (PMID 27795714, 2016). "A previous study also showed that RA and BMP4 synergistically induced the apoptosis of P19 embryonic carcinoma cells." (PMID 27795714, 2016). "Former studies demonstrated that BMP-4 and RA synergistically induce apoptosis in P19 embryonal carcinoma cells." (PMID 26173116, 2015). "In P19 embryonal carcinoma cells RA/BMP-4 induced apoptosis is mediated through the activation of RARs and not RXRs." (PMID 26173116, 2015). "Our results are in good accordance with data from Glozak and Rogers showing that in P19 embryonal carcinoma cells RA/BMP-4 induced apoptosis is mediated through the specific activation of RARα." (PMID 26173116, 2015). "Our results are in accordance with former findings demonstrating that in P19 embryonal carcinoma cells, RA and BMP-4 induce the activation of caspase-9, being upstream of caspase-3 in the RA/BMP-4 mediated apoptosis enzyme cascade." (PMID 26173116, 2015). "Given the differences in how each cell responds to activin A and BMP4 stimulation, we propose that the persistent or induced elevation of IPO5 may be a feature enabling the emergence of pluripotent embryonal carcinoma cells from testicular germ cells." (PMID 37048077, 2023).
glaucoma (8 papers, 2011 to 2025). Increased pressure in the eyeball due to obstruction of the outflow of aqueous humor. "BMP-2 is involved in the scleral remodeling process, and BMP-4 is associated with the onset and treatment of glaucoma and strabismus." (PMID 40696418, 2025). "Except for the effects of regulating TM cells, the protective effect of BMP-4 on retinal ganglion cells (RGCs) and axonal regeneration has been verified by observing RGCs’ survival in an experimental glaucoma mouse model." (PMID 40696418, 2025). "Gremlin overexpression has been found to inhibit BMP-4 thus leading to enhance TGF-β signalling and ECM deposition in primary open angle glaucoma." (PMID 24949470, 2014). "The essential role of these developmental glaucoma genes for the development of the anterior segment and in the development of TM implies that FOXC1, TGFβ2, and BMP4 are crucial for the normal development of drainage structures and preservation of normal IOP." (PMID 22736943, 2012). "In primary open angle glaucoma, elevated BMP antagonist expressed by TM cells inhibits BMP-4 antagonism of TGF-β2 and this inhibition leads to increased ECM deposition and elevated IOP." (PMID 21403850, 2011). "Another study indicated that BMP4 can block TGF-β2-stimulated ECM production in trabecular meshwork (TM) cells, while in primary open-angle glaucoma (POAG), gremlin may antagonize the natural role of BMP4 in TM cells." (PMID 35637963, 2022). "Other variants in genes for IFT172, DFNB31, PDHX, SALL2, BMP4 and GPR179 by WES were excluded as deleterious and pathogenic mutations, and none of them was reported as a stronger/convincing glaucoma causing variant in the literature." (PMID 34399712, 2021). "In vitro studies have shown that TGFβ2 and BMP4 act in concert to maintain a balance between ECM deposition and degradation, and may play an important role in glaucoma pathogenesis through mis-regulation of ECM synthesis and cross-linkage of ECM components of the TM." (PMID 22736943, 2012). "This represents the first association analysis of TGFβ2, BMP4, and FOXC1; the lack of association of common polymorphism does not provide evidence in support of the hypothesis that these genes play a significant genetic role in the pathogenesis of glaucoma among white British subjects." (PMID 22736943, 2012).
myopia (8 papers, 2009 to 2024). "On the contrary, in the current study, four novel truncation variants in BMP4 were identified as PPVs in eight patients with pathologic myopia from four families." (PMID 34926457, 2021). "Using similar strategy, four truncation variants in BMP4 (OMIM 112262) were detected in four unrelated families with pathologic myopia." (PMID 34926457, 2021). "A causative variant in the BMP4 gene with a severe myopia, ectodermal dysplasia, and cytopenia was found in a patient (PID95) in whom the altered immunological phenotype remains poorly explained by this mutation." (PMID 31031743, 2019). "This point reflects that truncation variants in BMP4 are highly related to pathologic myopia." (PMID 34926457, 2021). "We observed downregulation of BMP2 and BMP4 in chick myopia, similar to previous studies, and these genes are also implicated in human myopia." (PMID 39876870, 2024). "In humans, mutations in BMP-4 and BMP-7 have been reported to be associated with eye and brain developmental anomalies, including the development of myopia in specific families." (PMID 21403850, 2011). "Similarly, the frequency of BMP4 truncations in probands with early onset high myopia is significantly higher compared with the frequency in gnomAD (P = 1.23 × 10–7, Fisher’s exact test)." (PMID 34926457, 2021). "The snow-grain degeneration in the peripheral retina may be a characteristic sign specific for BMP4-related pathologic myopia." (PMID 34926457, 2021). "This characteristic phenotype has not been described previously in pathologic myopia so that it may be considered as a unique sign of pathologic myopia related to BMP4 truncation variants." (PMID 34926457, 2021). "These variants were confirmed by Sanger sequencing and cosegregated with pathologic myopia in eight patients from four families but in none of the unaffected individuals or any in-house controls, suggesting that BMP4 may be an important factor for pathologic myopia." (PMID 34926457, 2021). "In the current study, interestingly, all the four probands with these BMP4 truncations had early onset pathologic myopia, accounting for 4 of 928 probands with early onset high myopia, but in none of the 6,386 probands with other eye conditions (P = 2.58 × 10–4, Fisher’s exact test)." (PMID 34926457, 2021).
osteosarcoma (8 papers, 2009 to 2025). A usually aggressive malignant bone-forming mesenchymal neoplasm, predominantly affecting adolescents and young adults. "Expression levels of markers associated with human OSA including alkaline phosphatase, desmin, bone morphogenetic protein 4 and runt related transcription factor 2 were described in spontaneously arising canine osteosarcoma." (PMID 36288137, 2022). "Several studies have shown a link between EGFR and BMP4 in osteosarcoma." (PMID 36685868, 2022). "In a human osteosarcoma cell line, expression of FGF18 and BMP4 followed the same pattern as in the RNASeq data from SW1353 chondrosarcoma cells." (PMID 39963339, 2025). "A previous study demonstrated that PSA can significantly induce several osteogenesis‐induced genes, including CDH 11, BMP4, BMP8 and TGFβ, in osteosarcoma SaOS‐2 cells." (PMID 32508049, 2020). "To investigate if RBM39 also negatively regulates BMP4-dependent transcription in human cells, we transfected U2OS osteosarcoma cells with siRNAs to human RBM39 and a BRE-luc reporter." (PMID 27324164, 2016). "BMP-4 was highly expressed in all bone-forming clones, but was also expressed at rather high levels in a non-bone generating osteosarcoma clone (clone CMT-U353 B, clone 6) as well as in all of the carcinoma clones." (PMID 19771160, 2009).
type 2 diabetes (8 papers, 2011 to 2025). "In this paper, we aimed to test the impacts of BMP4 variants on type 2 diabetes in a large sample of Chinese population." (PMID 24350253, 2013). "The effect of BMP4 variants on type 2 diabetes which is definitely through impact on impaired insulin secretion or insulin sensitivity is rather ambiguous." (PMID 24350253, 2013). "Thus, it is imperative to further replicate the influence of the variant of BMP4 on type 2 diabetes and metabolic traits in other Chinese samples." (PMID 24350253, 2013). "We identified modest effects of BMP4 variants on the risk of type 2 diabetes." (PMID 24350253, 2013). "A significant association of BMP-4 rs17563 and FGF-3 rs1893047 to patients with PI and Type II diabetes mellitus was also identified in our analysis." (PMID 38840172, 2024). "Extracellular matrix, such as type I and IV collagen, or α-SMA, which is regulated by TGF-β and bone morphogenetic protein 4 (BMP4), is increased in the glomeruli of patients with type-2 diabetes and one of the important features of DKD." (PMID 34977254, 2021). "In the current study, we tested the effects of 10 tagging SNPs in BMP4 region on type 2 diabetes in a Chinese population." (PMID 24350253, 2013). "Nevertheless, up to now, there is no report focusing on the genetic association studies of BMP4 with type 2 diabetes and related clinical traits in East Asian population." (PMID 24350253, 2013). "Firstly, as the genetic effect of BMP4 variants on type 2 diabetes was mild, our samples may not have enough power to detect the association." (PMID 24350253, 2013). "Finally, although we found modest correlation between BMP4 variant and type 2 diabetes and related clinical characteristics, we did not perform a replicated research in another independent sample to confirm these results." (PMID 24350253, 2013). "Serum levels of BMP-4 increased progressively in rats transgenic for human islet amyloid polypeptide (HIP rats, a model of type 2 diabetes), resulting in a greater ability to induce BMP-dependent osteogenesis in calcifying vascular cells." (PMID 24170999, 2013). "Type 2 diabetes models based on p7kb-Bmp4Luc transgenic mice may be suitable for evaluating disease onset, and these transgenic mice may provide a useful tool for future toxicological screening studies, and for further studies to reveal the functions of Bmp4 in the pancreas." (PMID 21949805, 2011). "Additionally, the OPG rs2073617 SNP was significant among smokers, and the BMP-4 rs17563 and FGF-3 rs1893047 SNPs were significant among patients with type 2 diabetes." (PMID 41373620, 2025). "When analysing the study groups in relation to risk factors, OPG rs2073617 (p = 0.034) was more frequent in patients with PI who smoked more than 10 cig/day, and BMP-4 rs17563 (p = 0.018) or FGF-3 rs1893047 (p = 0.014) in patients with PI and Type II diabetes mellitus." (PMID 38840172, 2024). "Also, BMP-4 rs17563 (p = 0.018) and FGF-3 rs1893047 (p = 0.014) SNPs were more frequent in patients with PI and Type II diabetes mellitus." (PMID 38840172, 2024). "However, no studies have investigated the changes in BMP-4 levels in severely obese patients with type 2 diabetes after bariatric surgery." (PMID 24170999, 2013).